STAT3 (signal transducer and activator of transcription 3)
Diseases named in the same sentence as STAT3 in open-access papers (continued):
Sharing a sentence is not in itself a finding about the gene and the disease.
cardiovascular diseases (46 papers, 2011 to 2026). "It is known that STAT3 is the main member of the STAT family associated with cardiovascular diseases, and STAT3 activation in PAECs changes proliferative and survival phenotypes." (PMID 35269553, 2022). "Signal transducer and activator of transcription 3 (STAT3) protein has been linked to cardiovascular disease through multiple pathways in experimental and animal studies." (PMID 33568140, 2021). "Endothelial cell STAT3 has a key role in inflammation that underlies cardiovascular disease and impacts on cardiac structure and function." (PMID 31069236, 2019). "Unlike canonical drug-eluting stents that target mTOR or other pathways, PCK1 might be considered a potential target for cardiovascular diseases associated with vascular restenosis on the basis of its unique regulation of the STAT3/DRP1 pathway." (PMID 39262325, 2024). "Importantly, endothelial cell-released STAT3 has a key role in inflammation that underlies cardiovascular disease, and conversely, cardiomyocyte STAT3 is important for maintaining endothelial cell functions and the capillary integrity." (PMID 32508664, 2020). "Endothelial cell STAT3 has a key role in inflammation that underlies cardiovascular disease and impacts on cardiac structure, function, and genetic reprograming; conversely, cardiomyocyte STAT3 is important for maintaining endothelial cell function and capillary integrity." (PMID 31069236, 2019). "Cytokines, TNF α, IL-6, JAK1 and STAT3 as markers of inflammation response may play a major role in the risk for cardiovascular disease, which is also recognized as essential mediator of pathological aging." (PMID 25524239, 2014). "Although elevating epoxygenase products via sEH inhibition have been shown to be beneficial in a wide variety of animal models of cardiovascular disease, the mechanisms through which these effects are mediated are still largely unknown, although NF-κB and STAT3 have both been implicated." (PMID 22848834, 2012). "The natural anthraquinone derivative emodin has a promising application as a therapeutic agent for cardiovascular diseases, and it also has a significant inhibitory effect on STAT3 activation." (PMID 38402401, 2024). "JAK2/STAT3 is a classic inflammatory pathway, exacerbating vascular dysfunction and contributing to the progression of cardiovascular diseases." (PMID 39257845, 2024). "Using Myocardin/Stat3 (and analogs) to inhibit cardiomyocyte apoptosis holds promise as an effective therapeutic strategy for cardiovascular diseases." (PMID 29245928, 2017). "The Signal Transducers and Activators of Transcription (STATs) family is composed of 7 isoforms (STAT1; 2; 3; 4; 5A; 5B and 6) with STAT3 being the most important one in cardiovascular diseases." (PMID 21951574, 2011). "Previously our group reported that Bazedoxifene could inhibit phosphorylation of STAT3 by targeting IL‐6/gp130 interface in pancreatic cancer cells, which implied the potential effect of Bazedoxifene on IL‐6/gp130 signalling in cardiovascular diseases." (PMID 32164044, 2020). "Antagonism between the STAT1 and STAT3 pathways is well described, notably in cardiovascular diseases, but reciprocal regulation between STAT1 and STAT6 is an emerging field, and our results may be reflecting such a phenomenon mediated by HDL with regard to macrophage inflammatory state." (PMID 23991225, 2013). "Several studies have demonstrated that phytochemicals and natural plants exert a protective effect against cardiovascular diseases and regulate JAK2/STAT3 signaling." (PMID 40647133, 2025). "CRT and STAT3 molecules play important roles in the cardiovascular diseases, but the role of the CRT-STAT3 signaling pathway in the progress of DCM is little understood." (PMID 23818963, 2013).
cardiovascular diseases (continued). "In cardiovascular disease, the signal transducer and activator of transcription 3 (STAT3) pathway regulated the expression of p21 and ICAM-1 and cryptotanshinone inhibition of STAT3 prevented H19 consumption–mediated p21 induction and delayed aging." (PMID 37805704, 2023). "More importantly, bazedoxifene protected VECs from TNF-α-induced damage, suggesting that bazedoxifene may play a protective role in cardiovascular diseases through regulating the complex network connecting CD40, STAT3, AKT, ERK, and NF-κB signaling." (PMID 33381228, 2020). "IL-6 can bind the IL-6 receptor (IL-6R) and gp130, activate the Janus Kinase (JAK)-Signal Transducer and Activator of Transcription 3 (STAT3) signaling pathway, regulate inflammatory responses, and participate in the occurrence and progression of various cardiovascular diseases." (PMID 33099539, 2020). "This may suggest that the levels of STAT-3 activation in the cytosolic fraction do not affect S1P-mediated protection but it is possible that they could affect long-term recovery from cardiovascular disease, such as remodelling." (PMID 25000441, 2014).
adenocarcinoma (45 papers, 2012 to 2026). A common cancer characterized by the presence of malignant glandular cells. "STAT3 is persistently activated in about 50% of NSCLCs, especially in adenocarcinomas harboring activating mutations in EGFR which activate the gp130/JAK/STAT3 pathway by means of IL-6 upregulation." (PMID 27835873, 2017). "The few residual areas of ERG+ adenocarcinoma that retained Stat3 expression likely represent cells that escaped Stat3 knockout." (PMID 40858905, 2025). "So it can be inferred here that stimulation of the PI3K/Akt/mTOR signaling pathways not only promoted angiogenesis in adenocarcinoma cell lines via STAT3/5 phosphorylation but also inhibited the apoptotic activity of cells leading to angiogenesis." (PMID 31487123, 2019). "For instance, the expression of MMP 10 is regulated through the JAK2/STAT3 signaling in adenocarcinomas." (PMID 30220965, 2018). "Our data has also shown that leptin/LEPR signaling enhanced proliferation in the HEY3 and SKOV3 adenocarcinoma cell lines also via JAK2/STAT3." (PMID 29212170, 2017). "Activated STAT3 can repress NF-κB target gene expression by binding to and sequestering NF-κB in the cytoplasm of human adenocarcinoma cells." (PMID 26512722, 2015). "For example, in mice heterozygous for PTEN, development of adenocarcinoma is accelerated by the constitutive activation of STAT3." (PMID 24722453, 2014). "High levels of STAT3/5 were observed in over expressed PCNP adenocarcinoma cells." (PMID 31487123, 2019). "The association of high expression of MVP with better clinical outcome in adenocarcinoma may be attributed partly to the suppressive effect of MVP on STAT3 signaling pathway." (PMID 31092229, 2019). "For instance, IL-6 regulates MMP 10 through JAK2/STAT3 signaling in adenocarcinomas." (PMID 30220965, 2018). "STAT3 mRNA levels are increased and STAT3 phosphorylation is enhanced in adenocarcinomas." (PMID 26329521, 2015). "Considering the clinical relevance of the STAT3 signaling pathway in cervical carcinoma we focused the remaining studies of this work on the effect of endothelial cell-secreted IL-6 in the biology of adenocarcinoma cells." (PMID 24533454, 2014). "First, we examined the expression of NF-κB components, AICDA, Akt, JAK2/STAT3, and IL6 in PC9 (adenocarcinoma with the EGFR exon 19 deletion) and PC9/GR (adenocarcinoma with the EGFR-TKI-resistant with T790M mutation) cells, using Western blotting and RT-PCR." (PMID 35740609, 2022). "IL-6 treatment induces STAT3 phosphorylation and drives IFI16 transcription in a STAT3-dependent manner in human adenocarcinoma cell lines." (PMID 33505405, 2020). "It is worth noting that p27/JAK1/STAT3 axis is crucial in lung squamous carcinoma carcinogenesis but not adenocarcinoma." (PMID 39099000, 2024). "To further analyse the induction of PRMT5 expression by STAT3 in NSCLC cells, we generated STAT3-knockout (STAT3-KO) cells by using the CRISPR/Cas9 system in A549 (EGFR wild type, adenocarcinoma) and HCC827 cells (EGFR mutant, adenocarcinoma)." (PMID 38760429, 2024). "Importantly, this combination therapy regimen effectively reduced the levels of p‐STAT3, p‐AKT, and immunosuppression marker (ARG‐1 protein) and up‐regulated CD8 expression in adenocarcinoma lesions." (PMID 33283987, 2021). "Furthermore, fucoxanthin activated apoptosis via inhibition of PI3K/Akt/mTOR pathway in U87 and U251 human glioma cancer cells and induced apoptosis in adenocarcinoma SGC-7901 or BGC-823 human gastric cells involving downregulation of Mcl-1, STAT3 and p-STAT3." (PMID 32859058, 2020). "In previous studies cucurbitacin selectively inhibited phosphorylation of STAT3 but not ERK 1 or 2 (P44/42 MAPK), JNK-1 or AKT in NIH 3 T3 cells and adenocarcinoma cell lines." (PMID 24188277, 2013).
adenocarcinoma (continued). "The regulatory relationship between PCNP and STAT3/STAT4 has not been previously reported, although upregulated STAT3 and STAT5 were detected in adenocarcinoma cells overexpressing PCNP, and were found accountable for enhanced cell proliferative, migrated, and invasive abilities." (PMID 35468892, 2022).
kidney disease (44 papers, 2011 to 2025). "Considering that STAT3 plays a crucial role in the association between kidney disease and macrophages, we elucidated the effects of STAT3 inhibitor in an L-AKI model." (PMID 39367511, 2024). "Given our observation that STAT1, STAT3 and NFκB contribute to the aging transcriptional program, we used the genes for these transcription factors as candidates to find out if they are associated with either kidney function or renal disease susceptibility." (PMID 26678048, 2015). "STAT3 plays a significant role in the pathophysiology of renal diseases, moreover, the inhibition of STAT3 appears to be a useful strategy for mitigating renal damage." (PMID 40723823, 2025). "STAT3 is a crucial signaling molecule in tubular epithelial cells that prevents the progression of nephropathy and kidney fibrosis." (PMID 40723823, 2025). "STAT3 is a family member of inducible transcription factors, and its dysregulation is pivotal in various kidney diseases in humans and their mouse models." (PMID 39335615, 2024). "Studies using experimental models of kidney diseases have examined the role of Stat3 in terms of pathophysiology and the protective effects of Stat3 inhibition." (PMID 38293706, 2024). "Taken together, the present study identifies STAT3 interaction with P300 as a therapeutic target for the development of fibrotic kidney disease involving the activation of pericytes." (PMID 39335615, 2024). "STAT3 proteins are key downstream TFs induced by IL-6 cytokines involved in the pathogenesis of kidney disease that can be activated by binding to phosphorylated tyrosine residues on the cytoplasmic tails of activated cytokine receptors." (PMID 36246123, 2022). "STAT3 has only recently been investigated for its role in kidney diseases and demonstrated protective responses in animal models of ischemic AKI." (PMID 35733865, 2022). "Cell proliferation is often linked to the signal transducer and activator of transcription 3 (STAT3) pathway, which has been implicated in proliferation and fibrosis, specifically in kidney diseases." (PMID 35730565, 2022). "While beyond the scope of this study, further investigation of the role of STAT3 in SPLIS and the intersection of sphingolipids, STAT3, and kidney disease is clearly warranted." (PMID 33755599, 2021). "STAT3 is likely involved in many kinds of kidney diseases through regulation of the expression of target genes, especially the transcription factors involved in the development of CKD." (PMID 33407391, 2021). "Data generated from the current study indicates that p-STAT3 is likely to play an essential role in the progression of renal interstitial fibrosis in CKD resulted from various renal diseases." (PMID 31492196, 2019). "Taken together, STAT3 blockade serves as an important therapeutic intervention agent by exhibiting anti-inflammatory and anti-fibrotic effects, thereby alleviating LPS-induced kidney disease." (PMID 39367511, 2024). "In addition to genes related to kidney disease and immune response, we investigated the mRNA expression of STAT3 downstream genes." (PMID 39367511, 2024). "Interestingly, Stat3 was the most activated upstream regulator and is a well-characterized transcriptional regulator in kidney disease, including in the Tg26 mouse model." (PMID 39207915, 2024). "Thus, the present study identifies STAT3 interaction with P300 as a therapeutic target for developing fibrotic kidney disease involving the activation of pericytes." (PMID 39335615, 2024).
kidney disease (continued). "However, the impact of combining EGFR-clocking drugs with STAT3 inhibitors in kidney diseases remains to be tested." (PMID 39335615, 2024). "Our results provide important evidence that STAT3 blockers can protect renal cells by increasing their survivability and delaying fibrosis progression, highlighting their potential as therapeutic agents in renal diseases." (PMID 39367511, 2024). "Moreover, we reported the mechanism of STAT3 inhibitor against kidney disease, through previous researches." (PMID 39367511, 2024). "This may inhibit the signaling process mediated by IL-6, including the phosphorylation of STAT3, which is consistent with the view that targeting IL-6-dependent signaling can alleviate the harmful effects of kidney disease." (PMID 38179188, 2023). "PM2.5 induces early tubular epithelial injury by upregulating IL-6/STAT3 pathway and promotes EMT of renal tubular cells, suggesting that exposure to PM2.5 may increase the risk of developing kidney disease." (PMID 34884542, 2021). "Some studies have found that STAT3 signaling can control the EMT of renal tubular epithelial cells during renal injury, and dysregulated STAT3 may lead to renal disease, including inflammation and fibrosis." (PMID 34884542, 2021). "Previous data suggest that Gas6 induces mesangial cell proliferation via the latent transcription factor STAT3, which may be a therapeutic target for the treatment of renal disease." (PMID 23226259, 2012). "Among the predicted mRNAs, S1PR5, STAT3, TBR1, and BMPR1B were found to be related to some kidney diseases, as well." (PMID 36536378, 2022). "STAT3, a key member of the JAK/STAT axis, plays a very important role in various diseases, including renal diseases." (PMID 34434118, 2021). "Transcription factors that are targeted by Sirt1 and also play a significant role in the pathophysiology of kidney disease include Smad7, HIF-2α, and Stat3." (PMID 21858169, 2011). "Moreover, among the predicted targeted mRNAs, S1PR5, STAT3, TBR1 and BMPR1B were found to be related to some kidney diseases." (PMID 36536378, 2022). "Therefore, the results from the renal disease models suggest that elevated activity of STAT1, STAT3 and NFκB may have a deleterious effect on kidney physiology and function in old age." (PMID 26678048, 2015).
metabolic disorders (44 papers, 2013 to 2026). "Overactivated STAT3 was verified to cause hepatic glucolipid metabolic disorders, such as GLUT4 membrane traffic deficiency and cholesterol accumulation in MAFLD." (PMID 38617550, 2024). "We further analyzed the association of the polymorphisms of STAT3 with risk of metabolic diseases through case-control study." (PMID 25014397, 2014). "Demographic and biochemical characteristics of study on association between STAT3 and the risks of metabolic disorders." (PMID 25014397, 2014). "Genotype frequencies of STAT3 polymorphism rs1053005 and its association with the risks of metabolic disorders." (PMID 25014397, 2014). "Our main conclusions on the association between STAT3 polymorphisms and metabolic disorders remain statistically significant with the significance level of 0.025." (PMID 25014397, 2014). "Genotype frequencies of STAT3 polymorphism rs957970 and its association with the risks of metabolic disorders." (PMID 25014397, 2014). "Since STAT3 plays important roles in almost every aspect of energy metabolism, its variations might predispose the carriers to some risks of the metabolic diseases." (PMID 25014397, 2014). "Together, these findings identify JNK1 as a metabolic sensor linking intracellular fatty acid levels to STAT3-mediated oxidative metabolism in adipocytes, with potential implications for energy balance and metabolic disease." (PMID 41621714, 2026). "Adipose stem cell-derived exosomes were found to carry active signaling and STAT3 proteins that induce the conversion of obese mouse macrophages to anti-inflammatory M2 phenotype, thus alleviating IR and metabolic disorders in obese mice." (PMID 37223047, 2023). "The identification of these factors and the experimental evidences of direct interaction between phosphor-STAT3 and its target gene would hopefully illuminate our way to overcome leptin resistance and metabolic disorders." (PMID 33849593, 2021). "The literature suggests that MTOR is related to metabolic disorders and immune function, further suggesting that STAT3 may contribute to the occurrence of long-term amenorrhea through these mechanisms." (PMID 40137514, 2025). "STAT3, increasingly recognized for its role in cellular lipid uptake, has been shown to normalize lipid uptake when targeted, thus offering a potential target for addressing lipid-related metabolic disorders." (PMID 37630819, 2023). "SOCS3, an inhibitor of STAT3 which finally prevented inflammatory molecules transcription in many metabolic diseases, were found decreased after PPG injection and could be reversed by NaHS treatment." (PMID 33318871, 2021). "Third, since the two tagSNPs we examined only capture the common SNPs in STAT3 gene, we are not able to exclude the potential association between other rare variants of this gene and metabolic disorders related phenotypes." (PMID 25014397, 2014). "Since Reg3 family antimicrobial peptides have been reported to shape the composition of the gut microbiota in metabolic diseases, our findings warrant further exploration into whether the modulation of STAT3 activity alters microbial communities in mouse models of IBD." (PMID 33673239, 2021). "STAT3 is a member of the STAT protein family; it was identified as a transcription factor, and it participates in inflammation, tumorigenesis, and metabolic disorders." (PMID 35164031, 2022). "In conclusion, EAE may exert anti-PF effects associated with the structure of the gut microbiota, correction of amino acid metabolic disorders (notably tryptophan metabolism) and modulating JAK2/STAT3 signaling pathway in the lung." (PMID 42088464, 2026). "Thus, the JAK2/STAT3 signaling pathway seems to be one of the critical pathways regulating VSMC proliferation and resulting in the development of metabolic diseases." (PMID 35082965, 2022).
metabolic disorders (continued). "STAT3 is a transcription factor that can be activated by IL-6, EGF, and other cytokines, and plays a key role in various biological processes, such as inflammation, cell proliferation, migration, survival, and metabolic disorders." (PMID 27474168, 2016).